CLOCK (clock circadian regulator)
Diseases named in the same sentence as CLOCK in open-access papers (continued):
Sharing a sentence is not in itself a finding about the gene and the disease.
cancer (continued). "Therefore, by influencing the functions of CLOCK and BMAL1, CLK8 elicits improvements in aging, emotional disorders, and the effectiveness of cancer treatment." (PMID 36647780, 2023). "Additionally, the neuronal PAS domain protein 2 (NPAS2), a core circadian molecule analog of CLOCK, is upregulated in HCC and facilitates cancer cell survival." (PMID 34298842, 2021). "Indeed, apoptotic regulators DEC1 and DEC2 repress CLOCK/BMAL-induced transactivation of the PER1 promoter and modulate the response to cisplatin in several types of cancers, including human eSCC cell lines." (PMID 33810377, 2021). "Taken together, these studies support the emerging idea that BMAL1 and CLOCK have tumor promoting qualities in HGGs, while PER (and possibly CRY) may have tumor suppressing roles, though this is likely to be context and cancer dependent." (PMID 32631383, 2020). "Consequently, CLOCK and BMAL1 control the expression of the components of the RHOA-ROCK-CFL pathway, which alters the dynamics of F-actin/G-actin turnover and promotes cancer cell proliferation, migration, and invasion." (PMID 30287810, 2018). "Additionally, there is evidence showing that both oncogenes and tumor-suppressor genes are regulated by CLOCK and BMAL1 in tumor cells, which indicates regulatory roles of those two proteins in cancers." (PMID 30287810, 2018). "NAMPT thus is a target of both BMAL1:CLOCK and oncogenic MYC in Myc-driven cancers." (PMID 28674522, 2017). "Considering the stimulatory effect of CLOCK on PFKFB3 expression, it is likely that 3PO treatment also acted through reducing CLOCK expression to decrease PFKFB3 expression, thereby amplifying its anti-cancer effect." (PMID 27079271, 2016). "Of significance, CLOCK stimulated PFKFB3 expression through increasing the transcription activity of PFKFB3 promoter, which appeared to be responsible for distinct PFKFB3 rhythmic expression in cancer cells." (PMID 27079271, 2016). "How are the acute response to radiation and radiation-induced morbidity, cancer incidence, and mortality influenced by the absence of CLOCK?" (PMID 21566258, 2011). "Thus, it is possible that FOXP1 bound to gene-regulatory regions in the context of cancer could directly interfere with the rhythmic induction of these genes by the clock transcriptional activators, BMAL/CLOCK." (PMID 40349340, 2025). "Furthermore, genomic integrity may be compromised due to the influence of CLOCK, BMAL1, PER, and CRY on key signaling pathways such as c-Myc/p21 and Wnt/β-catenin, potentially leading to impaired DNA damage responses in cancer." (PMID 40700255, 2025). "CLOCK -BMAL1 and MYC-MAX both have very similar heterodimer structures and bind to largely identical promoter sequences, setting up the possibility that these two transcription factor heterodimers have overlapping functions and may compete in cancer cells." (PMID 34299381, 2021). "Hence, we speculate that the lower expression of PER1 in cancer cells can influence the activation and the intracellular distribution of CLOCK/BMAL1, rather than the alteration in expression level." (PMID 27602964, 2016). "For instance, CLOCK and PER3 were preferentially expressed in tumour and stomal cells, while PER1 was selectively expressed in immune cells and stromal cells but not in cancer cells." (PMID 39201344, 2024). "Unlike the mixed roles of CLOCK and BMAL1 in CSCs, period circadian regulator genes (e.g., PER2 and PER3), generally known as tumor suppressors in various types of cancer, have been shown to inhibit CSC maintenance and survival in tumors." (PMID 36430659, 2022). "When cells from the same dataset were stratified based on cellular type, CLOCK and PER3 were preferentially expressed in tumour and stomal cells, PER1 was selectively expressed in immune cells and stromal cells but not in cancer cells, and TEF was selectively expressed in CAF subtypes." (PMID 39201344, 2024).
cancer (continued). "Unlike CLOCK, BMAL1 has been reported as having oncostatic effects in cancer development." (PMID 26220712, 2015).
tumor (89 papers, 2014 to 2026). "The tumor formation rate of LLC1 cells (1 × 103) in mice treated with NE was significantly increased to 66.7% while the rate of LLC1 cells with CLOCK deficiency decreased to 0%." (PMID 39054537, 2024). "We harvested primary tumor cells and found that CLOCK deficiency substantially reversed the NE-elevated ALDH+ subpopulations and inhibited the diameter, number, and capacity of sphere formation in LLC1 syngeneic tumor primary cells." (PMID 39054537, 2024). "To further verify the role of CLOCK in NE-induced tumorigenesis, we determined the effects of CLOCK deficiency on tumor growth in LLC1 syngeneic mouse model undergoing NE treatment." (PMID 39054537, 2024). "Metallothionein (MT) expression controlled by CLOCK is associated with various endocrine diseases, mental diseases, and tumor diseases in humans." (PMID 36647780, 2023). "In the breast, PER and CRY are associated with better prognosis in ER+/HER2– tumours, yet CLOCK and NPAS2 are linked to better prognosis in the more aggressive ER–/HER2– tumours." (PMID 27590298, 2016). "Notably, the CLOCK gene and its associated protein demonstrated increased expression in more advanced tumor stages, suggesting its potential role in tumor progression." (PMID 39001398, 2024). "This indicates that the CLOCK gene and the protein that it encodes may be among the important factors of tumor progression." (PMID 39001398, 2024). "The results showed that the CLOCK deficiency reversed the NE treatment increased tumor volume." (PMID 39054537, 2024). "In addition, while our data demonstrate significant associations of higher CLOCK gene and protein expression with higher tumor grades, and of the presence of methylated promoter regions of PER1-3 genes with lower expression levels, we agree that these correlations do not inherently imply causality." (PMID 39001398, 2024). "Post translationally, CLOCK phosphorylation at Ser106 promotes nucleotide biosynthesis and tumor proliferation." (PMID 40725147, 2025). "For instance, studies have shown that mutations in CLOCK and BMAL1 can either enhance or suppress tumor growth, depending on the specific context and tissue type." (PMID 41174721, 2025). "Conversely, CLOCK inhibits apoptosis, as evidenced by decreased expression of apoptosis-inducing factors in CLOCK-defective mice, leading to enhanced tumor growth." (PMID 40046513, 2025). "Disruption of CLOCK expression can lead to altered immune cell function, impacting the body’s ability to mount effective anti-tumor responses." (PMID 40191195, 2025). "The expression of the CLOCK protein in tumor cells is significantly decreased in Wilms tumors, a rare kind of kidney cancer that mostly affects children." (PMID 38892035, 2024). "Inhibiting the BMAL1/CLOCK pathway can lead to dysregulation of important cell cycle regulators, namely Wee1 and p21, resulting in tumor cell death." (PMID 39335475, 2024). "Dual inhibition of LOX and CLOCK-OLFML3 axis extends the survival of PTEN-deficient GBM-bearing mice and leads to disease eradication in majority of tumor-bearing mice when combined with anti-PD1 therapy." (PMID 39352749, 2024). "The importance of these genes, belonging to the group of “CLOCK genes”, has been confirmed by their downregulation leading to cell cycle arrest and apoptosis of tumor stem cells." (PMID 38275375, 2023). "A large body of evidence has indicated that the CRG (CLOCK, BMAL1, PER, CRY, etc.)is associated with tumor progression, prognosis, and treatment response." (PMID 36895015, 2023). "One of the RORE clock genes, NPAS2, which was upregulated in the index CADM1-mutant tumour, is a paralog of CLOCK." (PMID 37612380, 2023). "The authors interpret this result as confirmation that the CLOCK-POSTN-TBK1 axis is involved in tumor angiogenesis and point to the need for further investigation into the precise molecular interaction between CLOCK, POSTN and TBK1." (PMID 38275375, 2023).
tumor (continued). "This is due to a growth proliferation rate upon circadian rhythm disruption because tumor suppressor and key cell cycle genes are under CLOCK control." (PMID 36556190, 2022). "A new study described an inverse correlation between the tumor suppressor activity of CLOCK and hypoxia, supporting the thesis that the suppression of CLOCK in tumor cells enhanced survival and reduced migration of the microglia." (PMID 36556190, 2022). "The in vivo results reveal suppression of tumor malignancy by enhancement of CLOCK expression in 4T1 cells." (PMID 33890571, 2021). "Disruption of the circadian clock function is linked to tumorigenesis in several studies with CLOCK and BMAL1 harboring tumor-suppressive roles." (PMID 35126099, 2021). "Low expression levels of CLOCK were detected in ALDH-positive 4T1 cells, and enhancing CLOCK expression in 4T1 cells attenuated tumor growth and invasive potential." (PMID 33890571, 2021). "Despite an increase in miR-96 and miR-183 levels, the deletion of miR-182 increased the expression of CLOCK and decreased tumor growth." (PMID 33890571, 2021). "These pro-tumor effects of the CLOCK gene are likely due to its transcriptional functions as well as to its intrinsic histone acetyltransferase (HAT) activity." (PMID 33114365, 2020). "The western blot results in LV-sh-UCA1 revealed that CLOCK expression was suppressed in tumor tissues." (PMID 31798345, 2019). "Restoration of BMAL1 and CLOCK circadian oscillation in lymphoma cells by using a PERK (protein kinase RNA-like endoplasmic reticulum kinase) inhibitor reduced tumor cell survival." (PMID 33089179, 2019). "To further investigate the roles of the circadian core protein CLOCK and BMAL1 in tumor cells, we performed immunofluorescence assays and found that both endogenous CLOCK (red) and BMAL1 (red) overlapped with RHOA (green), mainly in the cytoplasm." (PMID 30287810, 2018). "It should also be pointed out that 3PO treatment at CT7, but not at CT19, was more effective at decreasing the expression of PFKFB3 and CLOCK in implanted neoplasms." (PMID 27079271, 2016). "BMAL1 was down-regulated in both neighbouring and tumour tissue compared to normal mucosa, while CLOCK was slightly up-regulated in neighbouring tissue and slightly down-regulated in tumour." (PMID 27465361, 2016). "In the majority of the samples, the expression of BMAL and CLOCK was down-regulated in the tumour tissue compared to matched benign mucosa." (PMID 27465361, 2016). "This cluster revealed a lower expression or minor changes in the expression of BMAL1, CLOCK, tumour marker genes, cytokeratins and casein kinases." (PMID 27465361, 2016). "We performed transcription factor (TF) enrichment analysis on the identified key genes and found that TFs such as HAND1, RELA, and CLOCK were upregulated in the tumor margin, whereas members of the zinc finger family were predominantly upregulated in the tumor center." (PMID 40741331, 2025). "The result showed that CLOCK knock down inhibited the NE-enhanced tumor formation rates." (PMID 39054537, 2024). "Nevertheless, CLOCK protein levels are higher at higher tumor lesion stages (G2 > G3 > G4)." (PMID 39001398, 2024). "CLOCK/BMAL1 induces tumour promoting inflammation whereas RORα abrogates it." (PMID 38378853, 2024). "Although our previous studies have shown that LOX and CLOCK inhibition reduces tumor angiogenesis in GBM, further studies are needed to evaluate whether these treatments affect vascular architecture and vessel leakage in GBM tumors." (PMID 39352749, 2024). "Recent data from RCT CLOCK and CLOCK II reported how the decision to switch from the on-clamp to off-clamp approach may be influenced by factors related to tumor masses and their complexity." (PMID 38398084, 2024). "The knowledge of the CLOCK mechanism in tumors could be important for the progress of tumor therapy." (PMID 36556190, 2022). "Moreover, C18orf25, NUP160, DYNC1LI2, SYNJ1, MAPK1, and CLOCK were lowly expressed in tumor tissues." (PMID 36249009, 2022).
tumor (continued). "Moreover, enhanced expression of CLOCK was shown to exert a suppressive effect on the stemness and malignant properties of BCSCs, resulting in the prevention of tumor growth." (PMID 36430659, 2022). "However, both tumor-promotional and tumor-suppressive relevance are existing between CLOCK expression and outcome." (PMID 33890571, 2021). "Next, we investigated the anti-tumor effects of CLOCK in 4T1 cell-bearing mice." (PMID 33890571, 2021). "Moreover, CLOCK-expressing 4T1 cell-bearing mice had limited formation of tumor colonies in lung and bone marrow (p<0.01)." (PMID 33890571, 2021). "Besides, PER1 and CLOCK were reported as potential biomarkers for head and neck squamous cell carcinoma, whereas PER2 was reported to be associated with vital tumor-related genes in oral cancer." (PMID 34745328, 2021). "Knockout of miR-182 restored the expression of CLOCK, resulted in preventing tumor growth." (PMID 33890571, 2021). "Hence, miR-182 plays a major role in tumor biology and the post-transcriptional regulation of CLOCK." (PMID 33890571, 2021). "Circadian locomotor output cycles protein kaput (CLOCK), a direct target of miR-141, may act as a tumor suppressor by regulating the circadian clock, which can control the cell cycle in response to the DNA damage induced by gemcitabine." (PMID 33007962, 2020). "We noticed that CLOCK expression was suppressed by LV-sh-UCA1 in tumor tissues (p < 0.01)." (PMID 31798345, 2019). "Moreover, CLOCK has been shown to promote tumour angiogenesis and immunosuppression." (PMID 39915814, 2025). "In a subsequent step, we determined that CLOCK mRNA expression can also be regulated at the post-transcriptional level via miRNA molecules, as well as titers of hsa-miR-106-5p and hsa-miR-20b-5p, whose expression statistically significantly decreases with increasing tumor grade." (PMID 39001398, 2024). "Moreover, CLOCK could induce remodeling of the tumor microenvironment cells by disturbing the cellular metabolism, altering gene expression, and aberrantly activating signaling pathways." (PMID 37036639, 2023). "Additionally, we found that CLOCK was also reduced by tumor acidosis." (PMID 32316196, 2020). "In CRC, among the core circadian components, BMAL1, ROR, and PER members have been described as tumour suppressors, while CLOCK, NR1D, and CRY members have been described as tumour promoters." (PMID 40564218, 2025). "CRGs such as CLOCK and BMAL1 play pivotal roles in modulating the tumor immune microenvironment, influencing immune cell function and potentially contributing to immune evasion mechanisms." (PMID 40191195, 2025). "For instance, key CRGs such as CLOCK and BMAL1 have been shown to modulate the functional state of immune cells within the tumor microenvironment, thereby affecting the efficacy of immunotherapy." (PMID 40191195, 2025). "The studies published so far showed both oncogenic and tumour suppressor functions of BMAL1, CLOCK, PER1, PER2, PER3, CRY2, and REV-ERBβ." (PMID 38378853, 2024). "Research in this area is expected to advance understanding of circadian locomotor output cycles kaput (CLOCK) and brain and muscle ARNT-like protein 1 (BMAL1) in tumor diseases, and contribute to the development of new anti-tumor treatment strategies." (PMID 36647780, 2023). "Numerous studies have shown that circadian rhythm regulators, such as PER2, CLOCK, BMAL1, CRY1, and CRY2, act as tumor suppressors in the liver, ovaries, colon, and lung." (PMID 37524704, 2023). "The expression of BMAL1, CLOCK, Rev-Erbα, and PER2 in intraperitoneal macrophages regulated the expression levels of F4/80 and CD11c in tumor tissues." (PMID 35116071, 2022). "Mock-transduced or enhanced CLOCK-expressing 4T1 cells were implanted into the mammary fat pad of female BALB/c mice, and the tumor volume was measured every week." (PMID 33890571, 2021). "The authors demonstrated that the suppression of CLOCK and BMAL in tumor cells improved the survival and reduced migration of the microglia." (PMID 34199348, 2021).